NLGN4X (neuroligin 4 X-linked)
Description:
Cell surface protein involved in cell-cell-interactions via its interactions with neurexin family members.
Synonyms: KIAA1260; NLGN4; NLGN; HLNX; ASPGX2; AUTSX2; HNL4X
Tractability: Small molecule: it has a binding pocket of medium quality; it belongs to a druggable protein family. Antibody: its Gene Ontology location is reachable by antibodies, with high confidence; UniProt places it where antibodies can reach, with medium confidence; UniProt predicts a signal peptide or a membrane-spanning region. PROTAC: ubiquitination databases record sites on it.
Gene: Protein-coding gene on chromosome X (5,840,637 to 6,228,867, reverse strand). Ensembl gene ENSG00000146938.
Subcellular location: Cell membrane; Postsynaptic density membrane; Cell projection, dendritic spine; Cell projection, dendrite; Synapse
Pathways (Reactome):
Neuronal System: Neurexins and neuroligins
Gene Ontology:
Molecular function: cell adhesion mediator activity; chloride ion binding; neurexin family protein binding; protein binding; protein homodimerization activity; scaffold protein binding; cell adhesion molecule binding
Biological process: adult behavior; learning; modulation of chemical synaptic transmission; negative regulation of excitatory postsynaptic potential; presynaptic membrane assembly; regulation of synapse assembly; social behavior; synapse assembly; synapse organization; vocalization behavior; brainstem development; cell-cell junction organization; cerebellum development; neuron cell-cell adhesion; neuron differentiation; organ growth; presynapse assembly
Cellular component: cell surface; dendrite; excitatory synapse; GABA-ergic synapse; glutamatergic synapse; plasma membrane; postsynaptic density membrane; postsynaptic specialization membrane; synapse; asymmetric, glutamatergic, excitatory synapse; membrane; symmetric, GABA-ergic, inhibitory synapse; dendritic spine; neuron to neuron synapse
Gene-disease validity (ClinGen):
ClinGen rates the evidence that NLGN4X causes each of these diseases.
X-linked complex neurodevelopmental disorder (X-linked): Definitive. A complex neurodevelopmental disorder that is transmitted via X-linked inheritance, and is characterized by intellectual disability, autism and epilepsy.
Homologues: Orthologues: dog NLGN4X (99% identical), chimpanzee NLGN4X (98% identical), tropical clawed frog nlgn4x (91% identical), zebrafish nlgn4xa (83% identical), zebrafish nlgn4xb (76% identical), mouse Nlgn4l (46% identical), Caenorhabditis elegans ace-3 (19% identical), Caenorhabditis elegans ace-4 (19% identical), Drosophila melanogaster Jhe (19% identical), Drosophila melanogaster CG3841 (19% identical), Drosophila melanogaster Glt (19% identical), Caenorhabditis elegans cest-27 (19% identical), and 36 more. Paralogues in human: NLGN4Y (98% identical), NLGN1 (73% identical), NLGN3 (73% identical), NLGN2 (63% identical), CES1 (24% identical), CES5A (24% identical), CES4A (23% identical), CES2 (23% identical), ACHE (22% identical), BCHE (22% identical), CES3 (22% identical), TG (21% identical), and 1 more.
Diseases named in the same sentence as NLGN4X in open-access papers:
NLGN4X is named in the same sentence as 54 diseases in open-access papers, as found by Europe PMC text mining. Sharing a sentence is not in itself a finding about the gene and the disease. The quoted sentences say what the papers report.
autism (71 papers, 2005 to 2026). Persistent deficits in social interaction and communication and interaction as well as a markedly restricted repertoire of activity and interest as well as repetitive patterns of behavior. "NLGN4X is most strongly linked to autism; several missense and frameshift variants have been found, with the majority assumed to impair protein function seriously." (PMID 41395454, 2025). "NLGN4X harbors autism-linked mutations (e.g. R704C) and therefore, studying its post-translational modifications (PTMs) and their effects on synapse structure/function is significant." (PMID 40032531, 2025). "NLGN4X was identified as a single causative gene of rare familial nonsyndromic autism for the first time." (PMID 36747195, 2023). "Nlgn4X is most highly associated with autism, with multiple frameshift and missense mutations identified where most are thought to severely disrupt protein function." (PMID 35601025, 2022). "The mutations of NLGN4X are generally linked with autism and Asperger syndrome in different human populations." (PMID 30405681, 2018). "In 2003, a mutation in neuroligin 3 (NLGN3; p.R451C) and a mutation in neuroligin 4X (NLGN4X; p.D396 fs) were reported in two unrelated Swedish autism families." (PMID 28948087, 2017). "NLGN4X encodes a protein which belongs to a family of neuronal cell surface and causal factors for monogenic autism as well as directly impacts neurodevelopmental processes during the formation of neurons and their connections." (PMID 27434032, 2016). "Here, we performed a case-control study to assess the association between noncoding genetic variants in NLGN3 and NLGN4X genes and autism, in an Italian cohort of 202 autistic children analyzed by high-resolution melting." (PMID 27782075, 2016). "Using this method we identified associations with SNPs at the P<10−4 level in or near several genes previously implicated in autism: NLGN4X, RAPGEF4, RORA, FAM135B and CNTNAP2." (PMID 24204716, 2013). "Our data provide further evidence that coding sequence mutations at NLGN3 or NLGN4X that cause autism are very rare." (PMID 23020841, 2012). "Genome-wide linkage studies have implicated regions on the X chromosome, and identification of structural variants in genes such as neuroligin 4, X-linked (NLGN4X) demonstrate the potential role of X-linked genes in autism." (PMID 22050706, 2011). "Frameshift and nonsense mutations in NLGN4X have been linked to Asperger syndrome/autism [MIM 300495, 300497] and X-linked mental retardation [MIM300495]." (PMID 17517138, 2007). "Another autism mutation, that is, R87W in NLGN4X, also impaired its glycosylation profile and caused major loss in protein function, although this phenotype could be a downstream effect of protein misfolding." (PMID 37865312, 2023). "In patient AUT167, the deleted gene that seems to be associated with autism and ID is NLGN4X (whose protein participates in synaptogenesis and glutamatergic pathways), located in the region of susceptibility for autism and Asperger (OMIM #300497 and OMIM #300495)." (PMID 37107578, 2023). "The association of Nlgns with autism was first reported in a Swedish family with two affected siblings, where one of the siblings had a de novo missense mutation in the coding region of Nlgn3 and the other in Nlgn4X." (PMID 35601025, 2022). "Together, data suggested that mutations on NLGN3 and NLGN4X might increase the risk of autism while polymorphisms of different nucleotides in autism still need further investigation." (PMID 27992373, 2017). "For example, Xp22.3 deletions including NLGN4X have long been associated with autism." (PMID 26759715, 2016). "We provide evidence that noncoding polymorphisms on NLGN4X may be associated to autism, suggesting the key role of NLGN4X in autism pathophysiology and in its male prevalence." (PMID 27782075, 2016).
autism (continued). "The involvement of neuroligins in ASD has been firstly confirmed in two Swedish families by a de novo missense mutation (R451C) in NLGN3 and a frameshift mutation (1186insT) in NLGN4X causing premature protein termination (D396X), respectively associated with typical autism and Asperger’s syndrome." (PMID 27782075, 2016). "Also, a frameshift mutation in NLGN4X causing a premature stop codon was observed in all affected individuals in a large family, in which 10 males had X-linked mental retardation, 2 had autism, and 1 had pervasive developmental disorder." (PMID 26759715, 2016). "Moreover, deletion of the Xp22 fragment may be a potential cause of autism, since one of the neuroligin genes, NLGN4X, is present in this chromosome fragment." (PMID 38398873, 2024). "This seemingly explains why the disruption of the NLGN4X gene results in autism accompanying intellectual disability." (PMID 36747195, 2023). "For instance, an autism-related R101Q substitution neighboring the conserved N102 glycosylation site I can severely attenuate NLGN4X maturation, its cell-surface transport, and synaptic availability." (PMID 37865312, 2023). "We sequenced the NLGN3 and NLGN4X loci in a sample of 144 male individuals with a diagnosis of autism; all the patient samples were obtained from the multiplex AGRE repository." (PMID 23020841, 2012). "Overall, the interesting conclusion of an autism-linked mutation regulating NLGN4X PTM is not supported by the current evidence." (PMID 40032531, 2025). "In the Chinese ASD cases, there were no significant findings regarding SNPs along NLGN4 gene and autism risk, yet in Greek ASD cases, nine nucleotide changes in NLGN4X are found to be associated with autism." (PMID 25161627, 2014). "Although cognitive effects of reduced NLGN4X dosage have not been described in female carriers of these mutations, autistic features have been described as part of the 45, X TS neurocognitive phenotype, and three females with autism and deletions of distal Xp encompassing NLGN4X have been reported." (PMID 17517138, 2007). "Most other “pathogenic” and “likely pathogenic” CNVs do not overlap nor appear similar to CNVs listed in Decipher, but they do span “autism genes” listed in the SFARI GENE, and AutismKB databases, such as DMD, NEXMIF, NLGN4X, PRKN, and others." (PMID 35762097, 2022). "NLGN4X and NLGN4Y, as marker molecules of human autism, are considered to play an important role in the etiology of autism, the formation of synapses, and the transmission of information." (PMID 35847642, 2022). "Elsewhere, brothers with Tourette syndrome—one with autism as well, and the other with ADHD—had a three-exon deletion of NLGN4X." (PMID 27777633, 2016). "However, an independent study of 107 autism patients (102 males, 5 females) found no genetic variants for both X-linked genes NLGN3 and NLGN4X in ASD on a high functioning level by screening four polymorphisms and one novel synonymous variant." (PMID 27992373, 2017). "Although both patients had NLGN4X and VCX-A deletions, neither had speech defects, intellectual disability, autism, or social disorders." (PMID 32670353, 2020).
autism spectrum disorder (17 papers, 2010 to 2025). A spectrum of developmental disorders that includes autism, and Asperger syndrome. "It has been demonstrated that variants in NLGN4X are a potential pathogenic mechanism for male bias in autism spectrum disorder." (PMID 37106349, 2023). "The SNP rs3747333 and rs3747334 in Neuroligin 4X (NLGN4X) gene have been demonstrated to be associated with the susceptibility to Autism spectrum disorder (ASDs; MIM 209850), but the results are inconsistent." (PMID 31139237, 2019). "In human, genetic variants of the NLGN4X gene have been reported to be associated with autism spectrum disorder in Japanese and Han Chinese populations." (PMID 24313905, 2013). "Synaptic genes, NLGN3 and NLGN4X, two homologous members of the neuroligin family, have been supposed as predisposition loci for autism spectrum disorders (ASDs), and defects of these two genes have been identified in a small fraction of individuals with ASDs." (PMID 21569590, 2011). "Both genes, XG and NLGN4X, are related to autism spectrum disorders that are also appropriately distributed among these populations." (PMID 27042214, 2016).
Intellectual disability (10 papers, 2015 to 2025). "A case report of intellectual disability (ID) showed that neuroligin 4 X-linked (NLGN4X, Gene ID: 57502), histone deacetylase 8 (HDAC8, Gene ID: 55869), TATA-box binding protein associated factor 1 (TAF1, Gene ID: 6872), and USP9X genes were associated with XCI escape." (PMID 39891056, 2025). "To date, several NLGN4X variants associated with ASD and/or intellectual disability (ID) mainly in an X-linked recessive inheritance pattern have been reported, yet NLGN4X variants seem responsible for the pathogenesis in a limited population of ASD/ID." (PMID 36747195, 2023). "In this regard, a de novo base pair substitution (−335G>A) in the promoter region of NLGN4X, has been found in one autistic child with nonsyndromic mental retardation (NSMR)." (PMID 27782075, 2016). "Previous literature indicated that the relationship between NLGN4X mutations and intellectual disability could not be definitively established." (PMID 32670353, 2020).
Asperger syndrome (9 papers, 2007 to 2023). "In addition to ASD, there are some reports indicating that NLGN3 and NLGN4X are also relevant to Asperger syndrome, X-linked mental retardation, and Tourette syndrome." (PMID 22934180, 2012). "For example, NLGN4X mutations are involved in a wide spectrum of phenotypes, ranging from mild isolated ID without communication deficits to Asperger syndrome with normal intelligence." (PMID 22738402, 2012). "By screening for NLGN3 and NLGN4X mutations in subjects with ASD or Asperger syndrome (a type of ASD with higher cognitive ability and normal language), one study of 140 males and 18 females identified two affected brothers; one has ASD and another has Asperger syndrome in one Swedish family." (PMID 27992373, 2017).
Cognitive impairment (5 papers, 2015 to 2025). Abnormal cognition is characterized by deficits in thinking, reasoning, or remembering. "Otherwise, partial duplication of the NLGN4X gene (Xp22.32) is related to cognitive deficits." (PMID 37106349, 2023).
breast carcinoma (4 papers, 2017 to 2024). "EDN3 has been found upregulated in glioblastoma stem cells, melanoma, and breast cancer and similarly to NLGN4X, promotes tumor proliferation and invasiveness." (PMID 34572907, 2021). "Here we show that the expression of NLGN4X is significantly higher in several subset of breast cancer, according to the CCLE database." (PMID 29244827, 2017). "Our IHC data on breast cancer TMA shows NLGN4X is minimally present in adjacent normal breast tissue while that high NLGN4X expression was observed in breast carcinoma and lymph node metastasis." (PMID 29244827, 2017). "Based on these data, it is a good possibility that and NLGN4X can be used as a biomarker for breast cancer and for prediction of survival outcomes of patients with hormone positive, Her+ subtype and ER-, basal subtype." (PMID 29244827, 2017). "NLGN4X expression data for all breast cancer cell lines in the Cancer Cell Line Encyclopedia (CCLE) was analyzed." (PMID 29244827, 2017). "It is possible that NLGN4X can modulate the metastatic behavior of breast cancer cells, and possibly play a role in the ability of cancer cells to metastasize to distant sites." (PMID 29244827, 2017). "We used the cBioPortal database to evaluate the transcriptional expression from breast cancer tissue and observed that NLGN4X was altered in 25 out of 1080 patients." (PMID 29244827, 2017). "In this study, we sought to determine the expression of NLGN4X, its relevance and functional significance in breast cancer." (PMID 29244827, 2017). "Additionally, studies in human breast cancer cell lines showed that siRNA mediated knockdown of NLGN4X lead to induction of apoptosis." (PMID 38902533, 2024). "Authors showed that neuroligins were neural cell adhesion molecules that were implicated in hetero-topic cell adhesion and were highly expressed in blood vessels and implicated in the growth of glioma cells; they reported an increased expression of NLGN4X in breast cancer tissues." (PMID 38137332, 2023). "The gene expression data for all the breast cancer cell lines within the Comprehensive Cell Line Encyclopedia (CCLE) database was studied to see whether the pattern of NLGN4X expression could be confirmed in a larger dataset." (PMID 29244827, 2017). "Here we report increased expression of neuroligin 4X (NLGN4X) in breast cancer." (PMID 29244827, 2017). "We found NLGN4X was abundantly expressed in breast cancer tissues." (PMID 29244827, 2017). "Therefore, we decided to focus on the role of NLGN4X in breast cancer." (PMID 29244827, 2017). "NLGN4X might represent novel biomarkers and therapeutic targets for breast cancer." (PMID 29244827, 2017). "Inhibition of NLGN4X may be a new target for the prevention and treatment of breast cancer." (PMID 29244827, 2017). "Knockdown of NLGN4X expression by siRNA decreased cell proliferation and migration significantly in MDA-MB-231 breast cancer cells." (PMID 29244827, 2017).
Anxiety (3 papers, 2013 to 2024). Intense feelings of nervousness, tension, or panic often arise in response to interpersonal stresses. "Interestingly, their mother who also carried the deletion had anxiety and depression, suggesting that variants of NLGN4X might predispose to a range of neuropsychiatric phenotypes." (PMID 27777633, 2016).
attention deficit-hyperactivity disorder (3 papers, 2013 to 2015). A disorder characterized by a marked pattern of inattention and/or hyperactivity-impulsivity that is inconsistent with developmental level and clearly interferes with functioning in at least two settings (e.g. at home and at school). "In 2008, another familial NLGN4X truncating mutation was identified in two brothers with TS/motor tic, one with ASD and the other with attention deficit/hyperactivity disorder (ADHD) and a mother carrier with a learning disorder, anxiety, and depression." (PMID 24578685, 2014).
epilepsy (3 papers, 2014 to 2023). A brain disorder characterized by episodes of abnormally increased neuronal discharge resulting in transient episodes of sensory or motor neurological dysfunction, or psychic dysfunction. "Though some variants (8p23.2 duplication, Xp22.2p22.33 deletion, and NLGN4X) classified as likely pathogenic, the association with epilepsy has not been reported so far." (PMID 32477112, 2020). "NLGN4X is a gene located in the short arm of the X chromosome and is also known to be related to ASD and ID, but not with epilepsy." (PMID 32477112, 2020).
glioma (2 papers, 2022 to 2023). A benign or malignant brain and spinal cord tumor that arises from glial cells (astrocytes, oligodendrocytes, ependymal cells). "Mutations in XIE genes USP9X, NLGN4x, PLXNB3 (involved in axonal guidance and glioma invasion), SYAP1, SRPX2, and ZFX (ZFX-SMARCA1 fusion) occurred in non-MN1-BEND2, predominantly female cases." (PMID 35440587, 2022).